RNU6-340P (RNA, U6 small nuclear 340, pseudogene)
Gene: Small nuclear RNA gene on chromosome 18 (2,649,761 to 2,649,867, reverse strand). Ensembl gene ENSG00000200875.
Homologues: Orthologues: chimpanzee U6 (100% identical), macaque U6 (93% identical), rabbit U6 (87% identical), dog U6 (80% identical). Paralogues in human: RNU6-1145P (88% identical), RNU6-1181P (88% identical), RNU6-1209P (88% identical), RNU6-16P (88% identical), RNU6-35P (88% identical), RNU6-393P (88% identical), RNU6-46P (88% identical), RNU6-480P (88% identical), RNU6-1 (87% identical), RNU6-116P (87% identical), RNU6-11P (87% identical), RNU6-1316P (87% identical), and 1287 more.